BPI (bactericidal permeability increasing protein)
Diseases named in the same sentence as BPI in open-access papers (continued):
Sharing a sentence is not in itself a finding about the gene and the disease.
ulcerative colitis (2 papers, 2020). An inflammatory bowel disease involving the mucosal surface of the large intestine and rectum. "Both BPI floxed mice and BPI KO mice did not spontaneously develop colitis, indicating that BPI deletion within intestinal epithelial cells is not the cause of ulcerative colitis." (PMID 33552078, 2020).
autoimmune disease (1 paper, 2021). A disorder resulting from loss of function or tissue destruction of an organ or multiple organs, arising from humoral or cellular immune responses of the individual to their own tissue constituents. "To date, the roles of BPI in T-cell functions and autoimmune disease pathogenesis remain unknown." (PMID 34815797, 2021).
B cell lymphoma (1 paper, 2024). "Notably, BPI associated positively with high-grade B cell lymphoma (HGBL) and double-/triple-hit disease." (PMID 38233586, 2024).
bronchopneumonia (1 paper, 2019). Acute inflammation of the walls of the terminal bronchioles that spreads into the peribronchial alveoli and alveolar ducts. "IDV, BCoV and BPI-3 were mainly detected in association with other respiratory pathogens during bronchopneumonia in calves." (PMID 31195597, 2019).
chronic lung disease (1 paper, 2021). According to the definitions of the American and British Thoracic Societies, including pulmonary functional tests, X-rays, and CT scans for items such as fibrosis, bronchiectasis, bullae, emphysema, nodular or lymphomatous abnormalities. "Moreover, impaired lung function in these chronic lung diseases is independently associated with the production of autoantibodies against bactericidal/permeability-increasing protein (BPI)." (PMID 34142075, 2021).
colitis (1 paper, 2020). Inflammation of the colon. "In colitis model, the level of BPI was increased at bottom of colon crypts but decreased at the sidewall of crypt which BPI deficiency was at colon of BPI KO mice." (PMID 33552078, 2020). "The objective of this study was to understand the role of bactericidal permeability increasing protein (BPI) in the pathogenesis of experimental murine colitis." (PMID 33552078, 2020). "BPI KO mice subjected to DSS showed increased symptoms of experimental colitis, increased colonic mucosal damage, increased epithelial permeability, elevated levels of serum LPS, and a disrupted fecal microbiome as compared with WT mice." (PMID 33552078, 2020). "The BPI KO mice developed worse colitis than WT mice by increased colitis symptoms and colonic mucosal damage, elevated levels of serum LPS, and a disrupted microbiome." (PMID 33552078, 2020). "Acute colitis was induced in BPI KO mice and wild-type (WT) mice by subjecting the mice to 5% dextran sulfate sodium (DSS)." (PMID 33552078, 2020). "The results showed that BPI KO developed worse colitis than control mice, as evidenced by increased colitis symptoms and colonic mucosal damage, elevated levels of serum LPS, and a disrupted microbiome." (PMID 33552078, 2020). "Furthermore, we subjected wild-type (WT) mice and BPI KO mice to 5% dextran sulfate sodium and assessed the development of experimental colitis in these mice." (PMID 33552078, 2020). "In summary, our study constructed BPI KO mice, which were then subjected to dextran sulfate sodium (DSS) colitis." (PMID 33552078, 2020).
empyema (1 paper, 2019). An accumulation of pus in a body cavity, usually the pleural space. "Otherwise, the serum levels of BPI and AZU1 were similar between CPPE, empyema, and UPPE." (PMID 31215423, 2019).
Hepatitis (1 paper, 2021). Inflammation of the liver. "Notably, Lck-BPI Tg mice also spontaneously developed hepatitis, suggesting that hepatitis could be a consequence of the induction of exosomal BPI from SLE T cells." (PMID 34815797, 2021).
ischemia (1 paper, 2017). A hypoperfusion of the BLOOD through an organ or tissue caused by a PATHOLOGIC CONSTRICTION or obstruction of its BLOOD VESSELS, or an absence of BLOOD CIRCULATION. "BPI-Fold-Containing-Family-B-Member-4 (BPIFB4) protein is higher in healthy vs. non-healthy (frail) LLIs serum and its longevity-associated variant forced expression improves cardiovascular outcomes in ischemia mice models." (PMID 28121621, 2017).
lung diseases (1 paper, 2012). "Although the biology the PLUNC (recently renamed BPI fold, BPIF) family of secreted proteins is poorly understood, multiple array based studies have suggested that some are differentially expressed in lung diseases." (PMID 22767025, 2012).
meningitis (1 paper, 2018). A disorder characterized by acute inflammation of the meninges of the brain and/or spinal cord. "The protein level of BPI was significantly increased in both S. pneumoniae and N. meningitidis meningitis as compared to the control group." (PMID 30581431, 2018).
mouth ulcers (1 paper, 2023). "Ultimately, we identified 6 potential risk genes (BTN3A3, IL12B, BPI, FAM213A, PLXNB2, and IL22RA2) of mouth ulcers with altered protein abundances in the blood." (PMID 37369724, 2023). "In conclusion, we found strong evidence supporting six novel blood proteins (BTN3A3, IL12B, BPI, FAM213A, PLXNB2, and IL22RA2) associated with mouth ulcers." (PMID 37369724, 2023). "Second, by using Bayesian colocalization, two correlated signals with common causal variants can be estimated at specific sites, and the causative proteins of oral ulcers (BTN3A3, IL12B, BPI, FAM213A, PLXNB2, and IL22RA2) were validated." (PMID 37369724, 2023). "However, only six genes (BTN3A3, IL12B, BPI, FAM213A, PLXNB2, and IL22RA2) assembled the criterion (PPH4 > 75%) in the analysis of mouth ulcers, indicating a shared single variant with mouth ulcers." (PMID 37369724, 2023). "Following this analysis, the researchers identified 6 key genes, namely BTN3A3, IL12B, BPI, FAM213A, PLXNB2, and IL22RA2, which were related to the onset of mouth ulcers." (PMID 37369724, 2023).
nephritis (1 paper, 2021). Inflammation of renal tissue. "Lck-BPI Tg mice showed manifested class III of lupus glomerulonephritis (nephritis activity score: 4; chronicity score: 1)." (PMID 34815797, 2021).
nonalcoholic fatty liver disease (1 paper, 2025). "Increased expression of BPI-fold protein family proteins should be partially associated with inflammation and fibrosis accompanying nonalcoholic fatty liver disease (NAFLD)." (PMID 40415790, 2025).
Pleural effusion (1 paper, 2017). The presence of an excessive amount of fluid in the pleural cavity. "Among the five types of pleural effusions, the protein levels of BPI, NGAL, AZU1, and calprotectin in CPPE were highest and estimated (expressed as the mean values ± s.e.m)." (PMID 28642494, 2017). "Four novel upregulated candidates (BPI, NGAL, AZU1, and calprotectin) were selected and further verified using enzyme-linked immunosorbent assays (ELISAs) on 220 patients with pleural effusions due to different causes." (PMID 28642494, 2017). "The four novel proteins (BPI, NGAL, AZU1, and calprotectin) identified in pleural effusion fluid specimens were further verified by ELISA in samples from 176 patients with different pleural effusion aetiologies." (PMID 28642494, 2017). "According to the proteomics data and bioinformatics analysis, four proteins were selected as potential biomarker candidates, including BPI, NGAL, AZU1, and calprotectin, and their roles in pleural effusions have not been addressed before." (PMID 28642494, 2017).
sarcoidosis (1 paper, 2022). Sarcoidosis is a multisystemic disorder of unknown cause characterized by the formation of immune granulomas in involved organs. "Using an regression algorithm, we identified a panel of 11 IgM autoantiboides including BPI, Fibrinogen IV, Hemocyanin, Histone H2B, Histone H3, Matrigel, Prothrombin protein, Sm, SmD, TPO and Vimentin, which can efficiently distinguish between sarcoidosis and healthy controls." (PMID 36264970, 2022).
Sciatica (1 paper, 2021). Pain in the lower back and hip radiating in the distribution of the sciatic nerve. "AZU1, BPI, TCF7L2, and WFIKKN1 were upregulated in sciatica patients, while ANGPTL4, CRP, EREG, FAM19A4, FGF1, LOC100129216, PLXNB1, RLN1, and RXFP2 were downregulated." (PMID 34925462, 2021).
staphylococcus aureus infection (1 paper, 2020). An infectious process in which the bacteria Staphylococcus aureus is present. "This lack of a specific requirement for P. aeruginosa for anti-BPI autoantibody induction was confirmed in a consecutive cohort of bacteremic patients, in which anti-BPI IgG was also found in Staphylococcus aureus infection." (PMID 32747603, 2020).
infection (30 papers, 2007 to 2025). The state of being infected such as from the introduction of a foreign agent such as serum, vaccine, antigenic substance or organism. "Our results suggest that epithelial damage associated with infection act as a signal to induce BPI expression." (PMID 28861073, 2017). "To comprehend the role of an active bacterial invasion and inflammatory response in inducing BPI expression, we checked BPI expression in mice after infection with an invasion deficient mutant STMΔinvC." (PMID 28861073, 2017). "Overall, the lower infection incidence observed in opebacan-treated participants appears consistent with BPI’s antimicrobial properties as well as associations of BPI gene single nucleotide polymorphisms with infection risk after myeloablative HCT41." (PMID 26835003, 2015). "Diminished PRRs, IFN-signature, and BPI gene expression raises the possibility that impairments in these pathways contribute to the susceptibility of LBW term infants to infection." (PMID 23626859, 2013). "Since previous studies have shown that hs-CRP indicates the presence of infection, we speculate that infection may associate with BPI protein in asthmatic patients." (PMID 32565845, 2020). "Finally, immune factors prevent pathogenic infection in vertebrate gestational tissues, and our dataset identifies several candidate genes responsible for immune defence in the pregnant dunnart uterus (BPI, BPIFB1, GZMA and PRF1)." (PMID 29402916, 2018). "STMΔinvC (invasion deficient mutant) infection in mice couldn’t induce BPI expression in the ileum." (PMID 28861073, 2017). "Many of the selected genes were immune‐related and play a role in the host response against infection, such as BPI, PRSS33, S100A9, CLEC4E, and so on." (PMID 39692191, 2025). "Another model of human macrophages infected with M. tuberculosis revealed that BPI gene expression is significantly reduced during infection." (PMID 38672491, 2024). "Recently, it was demonstrated that the BPI gene expression significantly decreased during infection in a model of human macrophages infected with M. tuberculosis H37, the virulent strain." (PMID 38672491, 2024). "This infection contributes to the production of autoantibodies against BPI (anti-BPI), decreasing the BPI concentration in serum and the ability to kill the bacteria and inducing an exacerbated inflammatory response." (PMID 38672491, 2024). "This further supports the notion that the presence of autoantibodies to BPI restricts its function during infection." (PMID 33981306, 2021). "Twenty-four hours post-infection, cells were lysed and BPI expression was quantified by western blot." (PMID 28861073, 2017). "Twenty-four hours post-infection, RNA was isolated and BPI expression was quantified by real-time PCR." (PMID 28861073, 2017). "There was up to fourfold increase in BPI expression within 24 h post-SA infection compared to uninfected control." (PMID 28861073, 2017). "Mice were infected intraperitoneally with 108 CFU of Shigella flexneri and BPI expression was quantified in various regions of the intestine, 1-day post-infection." (PMID 28861073, 2017). "To explore the link between infection and BPI expression in intestinal epithelial cells, we analyzed the expression of BPI in Caco-2 cells upon bacterial infection." (PMID 28861073, 2017). "BPI levels were detected by western blotting after infection with STM, SHG, and E. coli in U937 macrophages." (PMID 27822215, 2016). "We next analyzed the intracellular interaction of BPI with STM by confocal microscopy during the course of infection." (PMID 27822215, 2016). "The time course of STM replication in macrophages with knocked down BPI showed that STM replication was higher in knocked down conditions within 6 h post-infection compared to untransfected controls." (PMID 27822215, 2016). "Notably, BPI expression was maintained in infected macrophages, further supporting this essential role during infection." (PMID 41154675, 2025).
infection (continued). "Likewise, overexpression of BPI in intestinal epithelial cells inhibits IL-8 secretion after infection with S. typhimurium." (PMID 39858883, 2025). "The role of BPI has been well demonstrated during infections caused by Gram-negative bacteria, such as Pseudomonas sp., E. coli, Salmonella typhimurium, Shigella sp., Klebsiella pneumoniae, and Enterobacter sp." (PMID 38672491, 2024). "BPI is expressed in intestinal epithelial cells, which is the first barrier against infection." (PMID 33552078, 2020). "BPI plays an important role in innate immunity against infection." (PMID 33552078, 2020). "Interestingly, BPI expression increased up to fivefold upon SA infection compared to uninfected control." (PMID 28861073, 2017). "We couldn’t detect any change in BPI expression upon infection with STMΔinvC or STMΔfliC in these mice compared to untreated control." (PMID 28861073, 2017). "Next, we checked BPI expression in TLR4 knockout mice after infection with STM (WT) bacteria." (PMID 28861073, 2017). "Previous reports show an increase in BPI expression in Canines upon infection with E. coli." (PMID 28861073, 2017). "Thereby, MDCK cells harbouring a protease deficiency which will not release virus after infection were infected with 500 PFU/well IAV in the presence or absence of different peptides derived from human or mouse BPI, respectively." (PMID 27273104, 2016). "This may indicate that Salmonella actively inhibits the recruitment of BPI to SCV during later stages of infection." (PMID 27822215, 2016). "Interestingly, BPI mRNA expression significantly increased in differentiated macrophages upon treatment with various PAMPs (LPS and flagellin) or infection with various pathogens (STM, STY, and SA)." (PMID 27822215, 2016). "For this purpose, we used a recombinant BPI protein and treated two different strains of E. coli, starting from an initial concentration of 150 × 103/mL colony forming units (CFUs), because it is a bacterial load above the values reported in infections of infants and adults." (PMID 39858883, 2025). "The induction of the release of AMPs including BPI by Influenza A virus directly acting against the incoming thread might be a mechanism how the immune system restricts the infection at an early stage during the infection process and may limit pathogenicity of the pathogen." (PMID 27273104, 2016). "ANCA specific for bactericidal permeability increasing protein (BPI-ANCA) are detected in people with CF, and correlate with infection with Pseudomonas aeruginosa." (PMID 32765284, 2020). "Further, STM infection in TLR4-/- mice displayed a significant increase in BPI expression compared to uninfected mice, but with respect to WT mice, STM mediated BPI expression is less in TLR4-/- mice." (PMID 28861073, 2017). "Interestingly, during later time points of infection (2–6 h) by which bacteria maintain a proper niche inside the macrophages, Salmonella-containing vesicles (SCVs), a significant lesser colocalization with BPI, could be observed." (PMID 27822215, 2016). "Anti-neutrophil cytoplasmic antibodies specific for bactericidal/permeability-increasing protein (BPI-ANCA) are frequent in CF patients and mainly develop in response to infection with Pseudomonas aeruginosa." (PMID 23346184, 2012). "Bactericidal/permeability-increasing protein (BPI) and lipopolysaccharide-binding protein (LBP) are a group of antibacterial proteins that play an important role in the host’s innate immune defense against pathogen infection." (PMID 37107584, 2023). "The survival of BPI KO mice to infection with Acinetobacter baumannii, a gram-negative bacterium, was also assessed." (PMID 33552078, 2020). "Conversely, there was no increase in BPI expression during SA infection (1 × 108 CFU intragastrically) and SA infection did not cause any damage to mice intestine." (PMID 28861073, 2017).
infection (continued). "Interestingly, BPI/LBP was up-regulated only after infection with live A. salmonicida but not in presence of formalin-killed A. salmonicida." (PMID 31231379, 2019). "Infection with STM, STY or treatment with different Pathogen Associated Molecular Patterns (PAMPs) viz LPS (100 ng), Flagellin (500 ng) and Heat Killed STM (HK STM) did not significantly influence BPI expression in Caco-2 cells." (PMID 28861073, 2017). "Furthermore, during the course of an infection, BPI interacted with Gram-negative bacteria, resulting in enhanced phagocytosis and subsequent control of the bacterial replication." (PMID 27822215, 2016).
bacterial infection (10 papers, 2015 to 2025). "Our studies revealed increased expression of BPI in human macrophages during bacterial infection and upon stimulation with various pathogen-associated molecular patterns, viz., LPS and flagellin." (PMID 27822215, 2016). "The BPI/LBP antimicrobial peptide is crucial for the host’s resistance to bacterial infection, which was also found in many teleost fish species, and the amount is species-specific." (PMID 37107584, 2023). "Further investigations concerning the pro-inflammatory functions of BPI are needed as they will contribute to the principle understanding of innate immunity against bacterial infections." (PMID 30581431, 2018). "In order to understand the in vivo regulation of BPI expression during the course of bacterial infection, we checked the expression of BPI in the murine intestinal epithelium." (PMID 28861073, 2017). "Similarly to IL-8, the two members of the tubular lipid binding proteins (TULIP) family lipopolysaccharide binding protein (LBP) and bactericidal/permeability-increasing protein (BPI) are increased in bacterial infections." (PMID 33233831, 2020). "The evolutionary relationship between SPLUNC1 and both LBP and BPI has long invited speculation that SPLUNC1 might have either pro- or anti-inflammatory effects in the context of a bacterial infection or other inflammatory stimulus." (PMID 25765466, 2015). "In this context, BPI protein may interact with mycobacterial LAM, promoting phagocytosis, inhibiting the production of TNF-α, and causing an anti-inflammatory effect, similar to that observed in GN bacterial infections." (PMID 41008681, 2025). "BPI-ANCA decreases innate antimicrobial response and contributes to prolonged GN bacterial infections and the development of chronic immunoinflammatory response typical for UC/PSC." (PMID 41008681, 2025). "In our current study, we show that BPI expression is increased in differentiated macrophages upon bacterial infection, whereas in undifferentiated monocytes, there was no significant increase in BPI expression." (PMID 27822215, 2016).